ZNF561 (zinc finger protein 561)
Description:
May be involved in transcriptional regulation.
Synonyms: MGC45408
Tractability: PROTAC: UniProt records ubiquitination sites on it; ubiquitination databases record sites on it.
Gene: Protein-coding gene on chromosome 19 (9,604,680 to 9,622,601, reverse strand). Ensembl gene ENSG00000171469.
Subcellular location: Nucleus
Subcellular location (Human Protein Atlas): Nucleoplasm
Pathways (Reactome):
Gene expression (Transcription): Generic Transcription Pathway
Gene Ontology:
Molecular function: DNA-binding transcription factor activity, RNA polymerase II-specific; RNA polymerase II cis-regulatory region sequence-specific DNA binding
Biological process: regulation of transcription by RNA polymerase II; regulation of DNA-templated transcription
Cellular component: nucleus
Genetic constraint (gnomAD): Loss-of-function variants: 16 observed, 18.34 expected, observed/expected ratio (o/e) 0.87, 90% interval 0.59 to 1.33. The upper end of that interval is the gene's LOEUF score, 1.33, which puts it in group 5 of 6, group 1 being the genes least tolerant of losing a copy. Missense variants: 580 observed, 594.48 expected, observed/expected ratio (o/e) 0.98, 90% interval 0.91 to 1.04. Synonymous variants: 190 observed, 197.5 expected, observed/expected ratio (o/e) 0.96, 90% interval 0.85 to 1.09.
Homologues: Orthologues: chimpanzee ZNF561 (97% identical), tropical clawed frog zfx (22% identical), zebrafish zfx (21% identical), rat Zfy1 (21% identical), mouse Zfy1 (20% identical), mouse Zfy2 (20% identical). Paralogues in human: ZNF562 (74% identical), ZNF256 (39% identical), ZNF304 (39% identical), ZNF583 (38% identical), ZNF480 (36% identical), ZNF792 (36% identical), ZNF79 (36% identical), ZNF570 (36% identical), ZNF549 (35% identical), ZNF551 (35% identical), ZNF587B (35% identical), ZNF548 (34% identical), and 26 more.
Diseases named in the same sentence as ZNF561 in open-access papers:
ZNF561 is named in the same sentence as 2 diseases in open-access papers, as found by Europe PMC text mining. Sharing a sentence is not in itself a finding about the gene and the disease. The quoted sentences say what the papers report.
colorectal cancer (1 paper, 2026). A primary or metastatic malignant neoplasm that affects the colon or rectum. "ZNF561 codes for zinc-finger protein 561, aberrant expression of which is associated with colorectal cancer." (PMID 41551726, 2026).
uveal melanoma (1 paper, 2023). A melanoma derived from melanocytes of the uveal tract. "For example, in contrast with the activation of upstream branch points and cryptic 3’ss reported in uveal melanoma, the activation of a downstream cryptic 3’ss in ZNF561 in SF3B1K700E cells correlates with the use of a more downstream branch point, thus expanding the range of mechanisms involved." (PMID 37562845, 2023).